BST2 (bone marrow stromal cell antigen 2)
Diseases named in the same sentence as BST2 in open-access papers (continued):
Sharing a sentence is not in itself a finding about the gene and the disease.
breast cancer (continued). "Mahauad-Fernandez and Okeoma recently described a mechanism by which BST2 dimerization activates ERK1/2 and phosphorylates and degrades BIM, preventing anoikis in breast cancer cells." (PMID 36016386, 2022). "Thus, targeting BST-2 may be a versatile option for the treatment of breast cancer patients." (PMID 36476230, 2022). "B49 and its analog B49Mod1 peptides, derived from the extracellular domain (ECD) of bone marrow stromal antigen 2 (BST-2), display anti-adhesion activity on breast cancer cells." (PMID 32155736, 2020). "One such factor is BST-2, which is an IFN-inducible type II transmembrane protein that is overexpressed in various cancers, including breast cancer." (PMID 32872253, 2020). "Further, the expression and promoter activity of BST2 are also controlled by signal transducer and activator of transcription 3 (STAT3) in tamoxifen-resistant breast cancer cells." (PMID 31957537, 2020). "BST-2 antibody-mediated ADCC has been shown to be potent in myeloma treatment and in breast cancer, BST-2 plays a direct role in driving breast malignancy." (PMID 25860442, 2015). "Because human breast cancer patients bearing tumors with high BST-2 mRNA have lower survival, we directly evaluated the role of BST-2 expression in cancer cells on the survival of tumor-bearing mice." (PMID 25499888, 2014). "As expected, we observed reduced colony numbers and colony size in mammary cancer cells with suppressed BST-2 (intermediate-sh137 and low-sh413) compared to cells expressing high BST-2 (shControl)." (PMID 25499888, 2014). "The BST2 expression was induced into MDA-231, a human breast cancer cell line with low BST2 expression." (PMID 19338666, 2009). "The level of BST-2 in breast cancer tumors is higher than cancer markers, but so far, no effective method has been developed to target BST-2." (PMID 36476230, 2022). "In line with the results from the breast cancer model, BST2 was not significantly deregulated in the transwell experiment, whereas the complement factor B (CFB) was 6-fold overexpressed under these conditions." (PMID 31963450, 2020). "Overexpression of genes such as IL11RA, BST2 and GAS6 were important for pathogenesis of many cancer types such as gastric cancer, breast cancer, and ovarian cancer, but high expression of these genes may be responsible for advancement of GBM." (PMID 31137733, 2019). "Previous studies have shown that endogenous BST-2 promotes non-proteolytic motility (migration) and proteolytic motility (invasion) of aggressive murine breast cancer cell line 4T1 and human MDA-MB-231 cells." (PMID 30514852, 2018). "Using a mouse model of breast cancer, we show that BST-2 promotes metastasis independent of the primary tumor." (PMID 30514852, 2018). "We also systemically used structure-function analysis of the BST-2 protein to identify the domain of BST-2 involved in proteolytic and non-proteolytic motility of breast cancer cells." (PMID 29299143, 2017). "Profile of BST-2 DNA hypomethylation in breast cancer subtypes as ranked by significant difference compared to normal breast tissue." (PMID 25860442, 2015). "In mice, orthotopic implantation of mammary tumor cells lacking BST-2 increased tumor latency, decreased primary tumor growth, reduced metastases to distal organs, and prolonged host survival." (PMID 25499888, 2014). "It is conceivable that BST2 may be an important regulator in the STAT3/BST2/IL6 pathway leading to increased cell migration and proliferation in the bone metastatic breast cancer." (PMID 19338666, 2009). "We demonstrated that the BST2 expression was significantly increased in human bone metastatic breast cancer tissues compared to human non-bone metastatic breast cancer and normal breast tissues by TMA." (PMID 19338666, 2009). "The BST2 expression in one bone metastatic breast cancer and seven non-bone metastatic breast cancer cell lines were also determined using real-time RT-PCR and Western blot assays." (PMID 19338666, 2009).
breast cancer (continued). "In our present study, we present a novel analysis of differential expressions of bone marrow stromal protein 2 (BST2) in the breast cancer with bone metastasis vs. breast cancer without bone metastasis." (PMID 19338666, 2009). "The expression of the BST2 gene was significantly increased in the bone metastatic breast cancer cell lines and tumor tissues compared to non-bone metastatic breast cancer cell lines and tumor tissues by real time RT-PCR, Western blot and TMA." (PMID 19338666, 2009). "Our results indicated that breast cancer patients with bone metastasis exhibited significantly increased serum BST2 as compared to breast cancer patients without bone metastasis as well as normal healthy individuals (p < .001)." (PMID 19338666, 2009). "Among the control group, 3 (7%) of 43 breast cancer patient without bone metastasis had significantly increased serum levels of BST2." (PMID 19338666, 2009). "We observed that 1 out of 30 (3.3%) non-bone metastatic breast cancer tissues and 11 out of 20 (55%) bone metastatic breast cancer tissues showed increased BST2 expression, but none of the 8 (0.0%) normal breast tissues displayed the increased expression." (PMID 19338666, 2009). "The breast cancer patients with bone metastasis exhibited significantly increased serum BST2 as compared to breast cancer patients without bone metastasis and normal healthy individuals (p < .0001)." (PMID 19338666, 2009). "It is conceivable that BST2 is an important regulator in the STAT3/BST2/IL6 pathway leading to increased cell proliferation, as well as osteoclastic bone destruction and/or production in the bone metastatic breast cancer." (PMID 19338666, 2009). "Overexpression of these BST-2 variants in cancer cells enabled us to identify the tyrosine residues in the BST-2 cytoplasmic tail as critical in mediating proteolytic and non-proteolytic mechanisms of breast cancer cell motility." (PMID 29299143, 2017). "They found overexpression of BST2 in the bone metastatic breast cancer tissues (compared to nonbone metastatic breast cancer tissues), as well as elevated BST2 levels in breast cancer patients with bone metastasis (compared to breast cancer patients without bone metastasis)." (PMID 26494939, 2015). "Because BST-2-expressing shControl cells metastasized more efficiently than BST-2-suppressed sh413 cells in vivo, we used a soft agar colony formation assay to examine the possibility that BST-2 is important for anchorage-independent growth of mammary cancer cells." (PMID 25499888, 2014). "Given that BST-2 is present in all breast tumors at different levels, and our results show that the effect of B49Mod1 is operative in all cancer cells tested, it seems that the role of BST-2 in breast cancer may be subtype independent and that B49Mod1 may be effective on all breast cancer subtypes." (PMID 29523843, 2018). "The inability of mammary cancer cells with suppressed BST-2 to efficiently colonize independent of attachment, along with the observed increase in tumor latency in mice implanted with BST-2-suppressed cells suggest that BST-2 action may be early and sustained in the process of mammary tumorigenesis." (PMID 25499888, 2014). "We then employed tissue array to further study the BST2 expression in human breast cancer using array slides containing 20 independent breast cancer tumors that formed metastatic bone lesions, 30 non-metastasis-forming breast cancer tumors, and 8 normal breast tissues." (PMID 19338666, 2009). "B49Mod1 does not have an effect on anchorage-independent growth of low BST-2 expressing non-tumorigenic HMLE and MCF10a cells that form little or no colonies, but inhibited growth of MDA-MB 134 luminal A breast cancer cell colonies despite low levels of BST-2." (PMID 29523843, 2018).
breast cancer (continued). "Although MMTV infects and causes mammary cancer in infected mice; nonetheless, infected cells do not produce high virus titer, and time to MMTV-induced cancer is rather long, suggesting that virus replication and spread may be restricted by host factors like BST-2." (PMID 22284121, 2012). "These experiments reveal that the BST-2 extracellular domain does not play a key role in cell motility; but we identify the BST-2 cytoplasmic tail YxY motif as indispensable in the invasion of aggressive breast cancer cell lines." (PMID 29299143, 2017). "The BST2 mRNA was significantly increased (P < 0.01) in the bone metastatic breast cancer cell lines, MDA-231BO compared to the normal breast cell line, MCF-10A, and the non-bone metastatic breast cancer cell lines, HTB-121, UACC812, MCF-7, T47D, MDA-468, BC-701 and MDA-231 by real time RT-PCR." (PMID 19338666, 2009). "The expression level of BST2 protein was also increased in bone metastatic breast cancer cell line, MB-231BO compared to the normal breast cell line, MCF-10A and non-bone metastatic breast cancer cell lines, HTB-121, UACC812, MCF-7, T47D, MDA-468, BC-701 and MDA-231 by Western blot assay." (PMID 19338666, 2009).
myeloma (16 papers, 2009 to 2025). "Studies indicate that BST2 expression is elevated in an array of neoplastic diseases, encompassing multiple myeloma, endometrial, and gastric malignancies, in addition to glioblastoma and primary pulmonary neoplasms." (PMID 41281378, 2025). "Known as a type II transmembrane protein, BST2 has been validated to play an oncogenic role in myeloma, breast cancer, lung cancer and kidney cancers 15-18." (PMID 36594082, 2023). "BST2, a type II transmembrane protein, exhibits oncogenic properties in diverse tumors such as PC, myeloma, breast, lung, and kidney cancers." (PMID 37628967, 2023). "We generated a mouse mAb specific to HM1.24 (CD317 or bone marrow stromal antigen 2: BST2) by immunization with the human myeloma cell line KPC-32." (PMID 24386306, 2013). "BST-2 was originally identified as a membrane protein in terminally differentiated human B cells of patients with multiple myeloma BST-2 is a 30-36 kDa type II transmembrane protein, consisting of 180 amino acids." (PMID 19737401, 2009). "BST2 (Bone marrow stromal cell antigen 2) was initially thought to be involved in normal and malignant B cell differentiation since this protein is expressed on bone marrow stromal cells and multiple myeloma cells." (PMID 22072961, 2011). "In addition, BST-2 expression levels are elevated in several cancers such as head and neck, breast, cervical, lung, endometrial, myelomas, and glioblastomas as well as lupus erythematosus (SLE) an autoimmune disease, suggesting that BST-2 could be an immunotherapeutic target for several diseases." (PMID 34025670, 2021). "Bone Marrow Stromal Cell Antigen 2 (BST2), a transmembrane glycoprotein initially identified as HM1.24 and later referred to as BST2 or CD317, has gained attention due to its elevated levels in multiple myeloma reported in 1994." (PMID 41281378, 2025). "BST2, a type II transmembrane protein also known as HM1.24/CD317, has been identified to be overexpressed in a variety of cell lines from different cancer types, including multiple myeloma, breast, lung, and kidney cancers." (PMID 26494939, 2015).
breast tumors (12 papers, 2013 to 2022). "In contrast, inherent TGFβ resistance characteristic of high grade breast tumors is a key factor underlying compromised BST2 regulation, and consequently its constitutive overexpression relative to non-malignant breast epithelium, and to most low and intermediate grade cancer cells." (PMID 23840623, 2013). "Although the level of BST-2 in breast tumors is higher than those of established cancer markers, there is no therapy targeting BST-2 in cancer cells." (PMID 32872253, 2020). "Clinical breast tumor specimens from a cohort of invasive breast cancer patients facilitated the correlation of BST-2 levels to disease severity." (PMID 30514852, 2018). "Almost all breast tumors express the antiviral protein BST-2 with 67%, 25% and 8.2% containing high, medium or low levels of BST-2, respectively." (PMID 28300825, 2017). "The data show that more breast tumors contain elevated BST-2 protein compared with the levels of estrogen receptor, progesterone receptor, HER2 or Myc." (PMID 28300825, 2017). "To probe into the regulatory mechanism of BST-2 overexpression in breast tumors, we analyzed BST-2 methylation beta-values from paired tumor and normal breast tissues." (PMID 25860442, 2015). "Here, we aimed to determine the source of BST-2 overexpression in breast tumors through in silico and in vitro analyses." (PMID 25860442, 2015). "We report that BST-2 expression in breast tumors and cancer cells is epigenetically regulated by hypomethylation or demethylation of specific CpG sites along the BST-2 gene." (PMID 25860442, 2015). "Meta-analyses of human epidemiological data revealed that in breast tumors and neoplastic epithelial cells, BST-2 expression is epigenetically regulated by DNA demethylation." (PMID 25860442, 2015). "In our meta-analysis study, we found that human breast tumors with elevated BST-2 mRNA are larger, more aggressive, and patients bearing such tumors have poorer survival." (PMID 25499888, 2014). "To link BST-2 expression in breast tumors to tumor aggressiveness, we performed BST-2 immunohistochemistry (IHC) using tumor tissues obtained from an unselected, hospital-based cohort of patients (n = 79) with invasive breast cancer (IBC) diagnosed at The University of Iowa between 1986 and 198929." (PMID 30514852, 2018). "Breast tumor cells and tissues that contain elevated levels of BST-2 are highly aggressive." (PMID 28300825, 2017). "We hypothesized that meta-analyses of BST-2 gene expression and BST-2 DNA methylation profiles would illuminate mechanisms regulating elevated BST-2 expression in breast tumor tissues and cells." (PMID 25860442, 2015). "Although the source of elevated BST-2 in breast tumors is unknown, our data suggest that BST-2 expression in breast epithelial cells derived from breast tumors was significantly higher than BST-2 in normal breast epithelial cells." (PMID 25499888, 2014). "Finally, a direct role for TGFβ in mediating AP2 binding to the BST2 promoter was confirmed in 3 independent primary breast tumor lines treated with the TGFβ inhibitor - SB 431542 prior to ChIP analysis." (PMID 23840623, 2013). "Given the role of BST-2 in innate immunity - including its role in NF-кB activation and subsequent transcription of NF-кB-dependent genes, as well as the presence of high levels of BST-2 in breast tumors, we hypothesized that BST-2 may promote mammary tumorigenesis." (PMID 25499888, 2014). "Here, we studied the clinical consequences of BST-2 expression in breast tumors, the functional role of BST-2 in mammary tumorigenesis, and the cellular basis for BST-2-mediated effect on mammary tumorigenesis." (PMID 25499888, 2014). "There are unique CpG sites corresponding to probes 3 to 9 from the Human Methylation 450 array and proximal to the BST-2 gene TSS that were demethylated across all breast tumor types, irrespective of their subtype classification." (PMID 25860442, 2015).
colorectal cancer (10 papers, 2015 to 2024). A primary or metastatic malignant neoplasm that affects the colon or rectum. "The presence of BST2 on macrophages is associated with increased colorectal carcinoma progression and tumor-associated macrophage (TAM) phenotype (M2 phenotype) infiltration." (PMID 39684750, 2024). "Overexpression of BST2 is associated with poor survival of esophageal, gastric, or colorectal cancer patients." (PMID 34692852, 2021). "A preclinical study in colorectal cancer showed that up-regulated BST2 promotes immunosuppressive TME by recruiting TAMs and inducing them into the M2 phenotype." (PMID 37628967, 2023). "In colorectal cancer, BST2 induces macrophage M2 polarization and promotes tumor progression." (PMID 39650066, 2024). "Of note, elevated BST2 is a plasma marker of colorectal carcinoma." (PMID 31574898, 2019).
COVID-19 (10 papers, 2021 to 2025). A disease caused by infection with severe acute respiratory syndrome coronavirus 2. "The number one hub gene was BST2, which was associated with COVID-19." (PMID 40429912, 2025). "Interferon response genes, including ISG15 and BST2, had increased expression in the same groups that also had p-PBs (adults with COVID-19, children with dengue)." (PMID 37638019, 2023). "Another gene in the IFN-I pathway, BST2, also showed upregulation in patients with COVID-19 compared with controls." (PMID 33677468, 2021). "Certainly, other molecules of the interferon pathways as MHC class I, CD38, BST-2 or CD123 should be analyzed in patients with COVID-19." (PMID 33825125, 2021). "For example, it could be interesting to investigate the influence of genetic polymorphism relevant to identify the involvement of several genes especially Serping 1 or BST2 on the severity of COVID-19." (PMID 34753980, 2021). "Importantly, several unreported elevated proteins in patients with COVID-19, such as RBP2 and BST2, which show anti-microbial activity, along with proteins involved in extracellular matrix remodeling, including MATN2 and COL6A3, were identified." (PMID 37047248, 2023). "In all patients who succumbed to COVID-19, we found increased expression of bone marrow stromal cell antigen 2 (BST2) and interleukin 1 receptor type 1 (IL1R1) independent of hospitalization time." (PMID 35163504, 2022).